SIX4 (SIX homeobox 4)
Description:
Transcriptional regulator which can act as both a transcriptional repressor and activator by binding a DNA sequence on these target genes and is involved in processes like cell differentiation, cell migration and cell survival. Transactivates gene expression by binding a 5'-[CAT]A[CT][CT][CTG]GA[GAT]-3' motif present in the Trex site and a 5'-TCA[AG][AG]TTNC-3' motif present in the MEF3 site of the muscle-specific genes enhancer. Acts cooperatively with EYA proteins to transactivate their target genes through interaction and nuclear translocation of EYA protein. Acts synergistically with SIX1 to regulate target genes involved in formation of various organs, including muscle, kidney, gonad, ganglia, olfactory epithelium and cranial skeleton. Plays a role in several important steps of muscle development. Controls the genesis of hypaxial myogenic progenitors in the dermomyotome by transactivating PAX3 and the delamination and migration of the hypaxial precursors from the ventral lip to the limb buds through the transactivation of PAX3, MET and LBX1. Controls myoblast determination by transactivating MYF5, MYOD1 and MYF6. Controls somitic differentiation in myocyte through MYOG transactivation. Plays a role in synaptogenesis and sarcomere organization by participating in myofiber specialization during embryogenesis by activating fast muscle program in the primary myotome resulting in an up-regulation of fast muscle genes, including ATP2A1, MYL1 and TNNT3. Simultaneously, is also able to activate inhibitors of slow muscle genes, such as SOX6, HRASLS, and HDAC4, thereby restricting the activation of the slow muscle genes. During muscle regeneration, negatively regulates differentiation of muscle satellite cells through down-regulation of MYOG expression. During kidney development regulates the early stages of metanephros development and ureteric bud formation through regulation of GDNF, SALL1, PAX8 and PAX2 expression. Plays a role in gonad development by regulating both testis determination and size determination. In gonadal sex determination, transactivates ZFPM2 by binding a MEF3 consensus sequence, resulting in SRY up-regulation. In gonadal size determination, transactivates NR5A1 by binding a MEF3 consensus sequence resulting in gonadal precursor cell formation regulation. During olfactory development mediates the specification and patterning of olfactory placode through fibroblast growth factor and BMP4 signaling pathways and also regulates epithelial cell proliferation during placode formation. Promotes survival of sensory neurons during early trigeminal gangliogenesis. In the developing dorsal root ganglia, up-regulates SLC12A2 transcription. Regulates early thymus/parathyroid organogenesis through regulation of GCM2 and FOXN1 expression. Forms gustatory papillae during development of the tongue. Also plays a role during embryonic cranial skeleton morphogenesis.
Synonyms: AREC3
Tractability: No criterion of Open Targets' tractability assessment is met for any kind of drug.
Gene: Protein-coding gene on chromosome 14 (60,709,539 to 60,724,351, reverse strand). Ensembl gene ENSG00000100625.
Subcellular location: Nucleus; Cytoplasm
Subcellular location (Human Protein Atlas): Nucleoplasm; Cytosol
Gene Ontology:
Molecular function: sequence-specific double-stranded DNA binding; DNA-binding transcription factor activity, RNA polymerase II-specific; RNA polymerase II cis-regulatory region sequence-specific DNA binding; DNA binding; DNA-binding transcription activator activity, RNA polymerase II-specific; DNA-binding transcription factor activity; sequence-specific DNA binding
Biological process: anatomical structure morphogenesis; fungiform papilla morphogenesis; generation of neurons; male gonad development; male sex determination; male sex differentiation; metanephric mesenchyme development; myotome development; negative regulation of apoptotic process; negative regulation of DNA-templated transcription; negative regulation of neuron apoptotic process; negative regulation of satellite cell differentiation; olfactory placode formation; pharyngeal system development; positive regulation of branching involved in ureteric bud morphogenesis; positive regulation of DNA-templated transcription; positive regulation of ureteric bud formation; protein localization to nucleus; regulation of branch elongation involved in ureteric bud branching; regulation of epithelial cell proliferation; regulation of transcription by RNA polymerase II; sarcomere organization; skeletal muscle fiber differentiation; skeletal muscle tissue development; tongue development; and 3 more
Cellular component: chromatin; cytoplasm; nucleus; transcription regulator complex
Genetic constraint (gnomAD): Loss-of-function variants: 22 observed, 46.48 expected, observed/expected ratio (o/e) 0.47, 90% interval 0.34 to 0.68. The upper end of that interval is the gene's LOEUF score, 0.68, which puts it in group 2 of 6, group 1 being the genes least tolerant of losing a copy. Missense variants: 866 observed, 964.34 expected, observed/expected ratio (o/e) 0.9, 90% interval 0.85 to 0.95. Synonymous variants: 413 observed, 407.51 expected, observed/expected ratio (o/e) 1.01, 90% interval 0.93 to 1.1.
Homologues: Orthologues: chimpanzee SIX4 (99% identical), macaque SIX4 (97% identical), pig SIX4 (95% identical), dog SIX4 (94% identical), guinea pig SIX4 (91% identical), rat Six4 (90% identical), mouse Six4 (90% identical), tropical clawed frog six4 (60% identical), zebrafish six4b (37% identical), zebrafish six4a (36% identical), Drosophila melanogaster Six4 (18% identical), Caenorhabditis elegans ceh-32 (17% identical), and 3 more. Paralogues in human: SIX5 (29% identical), SIX1 (19% identical), SIX2 (19% identical), SIX3 (18% identical), SIX6 (16% identical), ANHX (12% identical).
Diseases named in the same sentence as SIX4 in open-access papers:
SIX4 is named in the same sentence as 34 diseases in open-access papers, as found by Europe PMC text mining. Sharing a sentence is not in itself a finding about the gene and the disease. The quoted sentences say what the papers report.
colorectal cancer (7 papers, 2017 to 2024). A primary or metastatic malignant neoplasm that affects the colon or rectum. "The relationship between the immunohistochemical staining score of SIX4 in tissue microarray and clinical parameters suggests that SIX4 expression is associated with colorectal cancer recurrence, and tumor stem cells have been extensively studied as the key factor of tumor recurrence." (PMID 39309424, 2024). "SIX4 is primarily responsible for organ development, myogenesis and neurogenesis, and elevated levels of its expressions have been associated with poor prognosis in lung, breast and colorectal cancers." (PMID 37309005, 2023). "Immunofluorescence experiments showed that SIX4 is mainly expressed in the nucleus in the colorectal cancer cell line." (PMID 39309424, 2024). "Firstly, we compared the expression of SIX4 in four colorectal cancer cell lines as well as one normal intestinal epithelial cell line and found that SIX4 was upregulated in colorectal cancer cell lines." (PMID 39309424, 2024). "In tissuearray, SIX4 was significantly upregulated in colorectal cancer when compared to the para-cancer tissue." (PMID 39309424, 2024). "SIX4 expression is upregulated and has been shown to play a role in tumorigenesis and metastasis of lung, breast, colorectal cancer." (PMID 37888903, 2023). "SIX4 also appears to promote PI3K/AKT activation in colorectal cancer and activates STAT3 in breast cancer." (PMID 37888903, 2023). "It has been reported that SIX4 expedited metastasis in colorectal cancer by activating the PI3K/AKT signaling pathway." (PMID 35498155, 2022). "Intriguingly, recombinant human IL-6 stimulated SIX4 expression in colorectal cancer cell lines." (PMID 39309424, 2024). "Furthermore, we confirmed that knocking down SIX4 can inhibit the tumor stem cell phenotype in colorectal cancer (CRC)." (PMID 39309424, 2024). "SIX4 expression has been shown to be upregulated in colorectal cancer." (PMID 37888903, 2023). "The relationship of expression of SIX4 with clinical feature of colorectal cancer." (PMID 28584719, 2017). "However, what genes does SIX4 regulate to induce tumor stemness in colorectal cancer?" (PMID 39309424, 2024). "Our study first observes that activated SIX4 in inflammation induction drives the transformation of colorectal epithelium into inflammation and tumor, which demonstrates SIX4 as a significant therapeutic target in IBD and colitis-associated colorectal cancer (CAC) and CRC pathogenesis." (PMID 39309424, 2024). "However, the expression and clinical implication of SIX4 in colorectal cancer (CRC) remains unclear." (PMID 28584719, 2017). "Among the identified genes, SP5, SIX4, TREX2, and SPP1 were upregulated and were adverse prognostic factors in colorectal cancer." (PMID 39309424, 2024). "Targeting SIX4 alleviates both inflammatory bowel disease (IBD) and colorectal cancer (CAC) development in vivo." (PMID 39309424, 2024). "Clinical sample assays indicated that SIX4 is upregulated in inflammatory bowel disease (IBD) and colorectal cancer (CRC) tissues compared to normal colorectal tissues." (PMID 39309424, 2024). "Subsequently, we observed that SIX4 can bind to the promoter of p63 and induce DeltaNp63 expression, but not TAp63 in colorectal cancer." (PMID 39309424, 2024). "In addition, SIX1 and SIX4 have been shown to upregulate PI3K/AKT signaling in osteosarcoma and colorectal cancer, respectively, possibly through the downregulation of PTEN to further suppress apoptosis." (PMID 34490256, 2021). "In addition, elevated SIX4 also induces the expression of DeltaNp63, rather than wild-type p63, by binding to its promoter and thus facilitates the activation of tumor stemness signals, which ultimately leads to the formation of colorectal cancer." (PMID 39309424, 2024).
Alzheimer disease (4 papers, 2020 to 2026). A progressive, neurodegenerative disease characterized by loss of function and death of nerve cells in several areas of the brain leading to loss of cognitive function such as memory and language. "Researchers have reported the effects of WT1-AS on oxidative stress injuries (OSI) and the apoptosis of Alzheimer’s disease (AD) neurons and its specific correlation with the miR-375/SIX4 axis and WT1 expression mechanism." (PMID 33540574, 2021). "Besides, WT1-AS can regulate WT1 on oxidative stress injury and apoptosis of neurons in Alzheimer’s disease via inhibition of the miR-375/SIX4 axis." (PMID 34295352, 2021).
breast carcinoma (4 papers, 2016 to 2024). "Our analysis indicated that SIX1, SIX2, and SIX4 were associated with clinical prognosis of whole breast cancer population at mRNA level." (PMID 27399099, 2016). "Consistent with our results, SIX4 has been proposed to promote metastasis in breast cancer by activating EMT." (PMID 33481352, 2021). "SIX4 has been reported to promote metastasis through STAT3 activation in breast cancer." (PMID 33481352, 2021). "SIX1, SIX2, and SIX4 are activated in breast cancer patients." (PMID 27399099, 2016). "There is no significant publication bias for the following analysis: mRNA expression of SIX family members: breast cancer risk: SIX1: Begg test P = 0.707, Egger test P = 0.568; SIX3: Begg test P = 0.734, Egger test P = 0.474; SIX4: Begg test P = 0.707, Egger test P = 0.381." (PMID 27399099, 2016). "The tumor-supporting effects of SIX4 were also substantiated in hepatocellular carcinoma, non-small-cell lung cancer, and breast cancer." (PMID 35498155, 2022). "Sineoculis homeobox homolog (SIX) family proteins, including SIX1, SIX2, SIX3, SIX4, SIX5, and SIX6, have been implicated in the initiation and progression of breast cancer, but the role of each member in breast tumor is not fully understood." (PMID 27399099, 2016).
hepatocellular carcinoma (4 papers, 2021 to 2024). A malignant tumor that arises from hepatocytes. "For example, upregulation of SIX4 promotes tumour growth or metastasis in oesophageal squamous cell carcinoma, hepatocellular carcinoma and breast cancer." (PMID 36601689, 2023). "SIX4 belongs to the sine oculis homeobox family that has been reported to be required for tumour progression, such as leukaemia, oesophageal squamous cell carcinoma, hepatocellular carcinoma and pancreatic ductal adenocarcinoma." (PMID 36601689, 2023). "SIX4 expression has been detected in non-small cell lung, breast, colorectal, and hepatocellular cancers." (PMID 34490256, 2021).
lymph node metastasis (4 papers, 2016 to 2021). "Upregulation of SIX4 was associated with cell differentiation and lymph node metastasis in ESCC patients." (PMID 33481352, 2021). "SIX4 expression was associated with lymph node metastasis in ESCC patients (p < 0.05)." (PMID 33481352, 2021). "As one member of the sine oculis homeobox (SIX) homolog family, e SIX4 have been found up-regulated in colorectal patients, which is significantly related to lymph node metastasis, advanced Tumor Node Metastasis (TNM) stages, and unfavorable prognosis." (PMID 33028275, 2020). "In conclusion, the present study demonstrated that SIX4 overexpression in CRC tissues correlated with lymph node metastasis and predicted poor prognosis in CRC patients." (PMID 28584719, 2017). "Moreover, our study demonstrated that SIX4 expression correlated with lymph node metastasis and TNM stage in TCGA database, which was validated in the GSE5206, GSE14333, and GSE39582 cohorts." (PMID 28584719, 2017). "In addition, SIX4 expression significantly correlated with lymph node metastasis and advanced Tumor Node Metastasis (TNM) stages." (PMID 28584719, 2017). "SIX4 and SIX6 were linked to the lymph node metastasis (LNM)." (PMID 27821176, 2016). "However, the SIX4 mRNA level significantly correlated with lymph node metastasis and TNM stages." (PMID 28584719, 2017). "The results from GSE5206 and GSE39582 showed higher SIX4 expression in lymph node metastasis samples compared with that in negative metastasis samples." (PMID 28584719, 2017).
bladder cancer (3 papers, 2021 to 2023). "Meanwhile, the overexpression of SIX4 diminished the effects of miR-203a on bladder cancer cells in vitro." (PMID 37627900, 2023). "The downregulation of SIX4 in bladder cancer cells inhibit cell migration and invasion, and induce G2/M phase cell cycle arrest and apoptosis." (PMID 37627900, 2023). "SIX4 has been identified as a target of multiple microRNAs in different cancers, including gastric cancer, glioblastoma multiforme, and bladder cancer." (PMID 35498155, 2022). "The expression ratios of miR-203a/SIX4 may be a useful as a prognostic biomarker for bladder cancer." (PMID 37627900, 2023). "Moreover, it has been reported that downregulation of SIX4 led to bladder cancer cell cycle arrest and apoptosis." (PMID 33481352, 2021).
non-small cell lung carcinoma (3 papers, 2021 to 2024). A group of at least three distinct histological types of lung cancer, including non-small cell squamous cell carcinoma, adenocarcinoma, and large cell carcinoma. "In addition, miR‐621 was found to inhibit the malignant progression of non‐small cell lung cancer (NSCLC) by targeting SIX4, indicating that SIX4 functions as an oncogene in NSCLC." (PMID 33481352, 2021).
colon cancer (2 papers, 2023 to 2024). "Our analysis of colon cancer patient data indicated that tumors with high SIX4 expression were significantly enriched in the Inflammatory Response pathway and that SIX4 expression was positively associated with CD8A expression." (PMID 37888903, 2023). "Further, we used in vivo siRNA therapy (polyethyleneimine based transport systems) in mice models of DSS-induced colitis and AOM plus DSS-induced colon cancer to clarify the function of SIX4 in the progression of IBD and CAC." (PMID 39309424, 2024). "Analysis of The Cancer Genome Atlas (TCGA) colon cancer dataset is consistent with a role for SIX4 in controlling STING-dependent tumor clearance." (PMID 37888903, 2023). "Taken together, our results implicate that SIX4 is a principal regulator of STING expression in colon cancer cells, providing an additional mechanism and genetic marker to predict effective immune checkpoint blockade therapy responses." (PMID 37888903, 2023). "Nevertheless, SIX4 regulation of STING expression appears to play a significant role in colon cancer." (PMID 37888903, 2023). "Moreover, upregulated SIX4 enhances the stemness of colon cancer cells by promoting the DeltaNp63 signal, which further accelerates tumorigenesis in CRC." (PMID 39309424, 2024). "Here we show that SIX4 is a key regulator of STING expression in colon cancer cells." (PMID 37888903, 2023). "It seems likely that patients with colon cancer with high SIX4 expression may have immunogenic tumors with infiltration of CD8+ T cells." (PMID 37888903, 2023). "Data analysis of human patients with colon cancer support the hypothesis that SIX4 increases STING/type I IFN signaling and enhances inflammatory responses, which facilitates T-cell infiltration and antitumor immunity." (PMID 37888903, 2023). "Finally, analysis of The Cancer Genome Atlas colon cancer dataset indicated that tumors with high SIX4 expression were significantly enriched in the Inflammatory Response pathway." (PMID 37888903, 2023). "We have identified SIX4 as a significant regulator of STING expression in colon cancer cells." (PMID 37888903, 2023). "Therefore, our studies add an additional layer to SIX4 function in regulating colon cancer progression and identify it as a potential target for enhancing immunotherapy." (PMID 37888903, 2023). "We examined the relationship between SIX4 expression and STING-dependent inflammatory activities in human colon cancer by mining RNA-seq data from TCGA-COAD." (PMID 37888903, 2023). "Our studies demonstrate that SIX4 is an important regulator of STING expression, providing a genetic marker or a therapeutic target to predict or enhance immune checkpoint blockade therapy responses in colon cancer." (PMID 37888903, 2023). "Taken together, our studies demonstrate that SIX4 controls STING expression and activation in colon cancer cells, providing an additional mechanism and a potential clinical genetic marker to predict effective response of patients with colon cancer to immune checkpoint blockade therapies." (PMID 37888903, 2023).
esophageal squamous cell carcinoma (2 papers, 2017 to 2021). Esophageal squamous cell carcinoma (ESCC) is a type of esophageal carcinoma (EC) that can affect any part of the esophagus, but is usually located in the upper or middle third. "However, there have been few studies on the function of SIX4 in esophageal squamous cell carcinoma (ESCC)." (PMID 33481352, 2021).
gastric cancer (2 papers, 2022). A primary or metastatic malignant neoplasm involving the stomach. "For example, circRNA hsa_circ_0000670 facilitated gastric cancer development through regulating SIX4 expression via sponging miR-384." (PMID 35164763, 2022).
lung adenocarcinoma (2 papers, 2016 to 2021). A carcinoma that arises from the lung and is characterized by the presence of malignant glandular epithelial cells. "SIX4 controlled the expression of oncogenes, and it correlated with higher stages of the tumor, poor survival in NSCLC, and worse rate of relapses in lung adenocarcinoma." (PMID 34262872, 2021).